IL1B (interleukin 1 beta)
Diseases named in the same sentence as IL1B in open-access papers (continued):
Sharing a sentence is not in itself a finding about the gene and the disease.
Obesity (continued). "In summary, it is likely that the two inflammasome sensors, NLRP1 and NLRP3, exert opposite effects in obesity; NLRP1 cleavage of IL-18 acts to limit metabolic dysfunction, while NLRP3 activation of IL-1β is detrimental and promotes glucose intolerance." (PMID 29515457, 2018). "In obesity-prone mice, the inhibition of hypothalamic fractalkine reduces obesity-related inflammatory activity as demonstrated by the reduction of TNF-α and IL-1β levels and the decreased recruitment of bone marrow-derived cells to the hypothalamus." (PMID 30618568, 2018). "IL-1β represents an insulin resistance-promoting adipokine with strong pro-inflammatory properties and AT expression is upregulated in HFD-induced obesity and insulin-resistant mouse models." (PMID 28932870, 2018). "The asthma and obesity groups showed an increase in cytokine of IL-17A, IL-4, IL-6, TNF, IL-1β and IL-18 in the BALF compared with normal controls." (PMID 29160418, 2017). "The expression levels of IL-1β mRNA and NLRP3 mRNA in lung tissue of the obesity and asthma groups were increased." (PMID 29160418, 2017). "Obesity-induced danger signals have been reported to activate the NLRP3 inflammasome and induce the production of IL-1β in adipose tissue in T2D patients and in mice fed a high-fat diet." (PMID 28115020, 2017). "To further investigate the molecular mechanism responsible for TMAO-induced cardiac fibrosis and dysfunction in WD-induced obesity, we measured the protein levels of pro-inflammatory cytokines TNF-α and IL-1β and anti-inflammatory cytokine IL-10 in the hearts." (PMID 28377725, 2017). "The excess accumulation of M1 macrophages within VAT is now understood to be the primary source of circulating proinflammatory cytokines IL-1β, IL-6, and TNF-α that contribute to the state of chronic, low-grade inflammation observed during obesity." (PMID 28400677, 2017). "Other studies have shown that inflammatory cytokines known to be elevated in obesity (e.g. IL1β, TNF-α, and IL6) impair lymphatic collecting vessel contraction capacity, and, in the case of IL1β, do so by induction of iNOS expression." (PMID 26796537, 2016). "It is well accepted that obesity has an inflammatory status, including an elevation of the proinflammatory cytokines, TNF-α, IL-1β, and IL-6 in adipose tissues and sera." (PMID 27095436, 2016). "NAFLD pathophysiologic processes linking obesity enhanced circulating concentrations of pro-inflammatory cytokines and factors (e.g., TNF-α, IL-6 and IL-1β)." (PMID 27483220, 2016). "Here, the authors show that obesity promotes breast cancer through the recruitment of macrophages with activated NLRC4 inflammasome, which activate IL-1β production, resulting in VEGFA expression in adipocytes and angiogenesis." (PMID 27708283, 2016). "It is well known that obesity is a chronic inflammatory status with increased serum levels of tumor necrosis factor-α (TNF-α), interleukin-6 (IL-6), and IL-1β." (PMID 27070576, 2016). "HF fed animals developed obesity, insulin resistance and seemed to present increased plasma levels of proinflammatory cytokines (MCP-1 and IL1β)." (PMID 27134637, 2016). "Both IL-6 and IL1B were identified as highly differentially co-expressed genes across tissues between MHO and MUO individuals, showing their potential role in obesity-induced disease development." (PMID 27907186, 2016). "It follows that the balance of cytokines, given by proinflammatory (such as IL-1β, IL-6, TNF) and anti-inflammatory effector molecules (such as IL-10) depends on both ageing and obesity-related dietary patterns." (PMID 26421054, 2015). "We found that obesity and periodontal indicators showed weak positive correlations, and LDL and BMI accounted for 19.1 % of the variance in IL-1β in the GCF of obese subjects." (PMID 26385382, 2015). "In the present study, obesity induced an increase in the serum concentrations of TNF-α, IL-6 and IL-1β in the ob/ob group." (PMID 26714835, 2015).
Obesity (continued). "Obesity is characterised by low-grade inflammation, reflected, in part, by increased expression of circulating (TNF-α) and local (TNF-α, IL-1β) proinflammatory cytokines in diet-induced obese mice." (PMID 26618193, 2015). "Therefore, the results herein suggest that IL-1β signaling mediates hepatocyte TG accumulation by driving the denovo lipogenic signaling pathway in obese mouse livers and that IL-1β represents a promising therapeutic target in the treatment of obesity-induced NAFLD." (PMID 25216251, 2014). "IL-6, IL-1β and APOH were identified as regulatory factors involved in blood coagulation and platelet activation in zebrafish and mammalian obesity." (PMID 20961460, 2010). "Both proinflammatory cytokines, IL-1β and IL18, are elevated in adult obesity and share a similar signal transduction pathway." (PMID 20169140, 2010). "Thus, increased IL-1β production may be involved in the development of obesity." (PMID 19398847, 2009). "In the present study,we examined whether resistin TNF-α, IL-6, and IL-1β mRNA levels from human peripheral mononuclearcells are altered in type 2 diabetes and whether they correlate withcirculating resistin levels and with indices of obesity or insulin resistance." (PMID 19125180, 2008). "In an obesity-related study, AMPK phosphorylates the SUCLA2 metabolic enzyme to restrict glutaminolysis, thereby reducing succinate accumulation and blocking NLRP3 inflammasome activation, which ultimately attenuates pro-IL-1β transcription." (PMID 41508030, 2026). "Higher levels of the IL-1β/IL-10 ratio were observed in the subgroups with obesity than in the normal weight subgroups, regardless of gender." (PMID 41602164, 2026). "Analyzing the levels of pro-inflammatory cytokine synthesis in the liver by Western blotting, in the case of IL-1β, two-way ANOVA analysis revealed significant effects of obesity (F = 8.935; p = 0.0174) and OEA-DS administration (F = 7.157; p = 0.0281), but not their interactions." (PMID 40265441, 2025). "In addition, our team has studied the inflammation in taste bud cells and demonstrated that diet-induced obesity or LPS-triggered inflammation increased TNF-α, IL-1β, and IL-6 expression, both at mRNA and protein levels, in taste bud cells." (PMID 40284173, 2025). "Likewise, in females with obesity, vaccinated mice had significantly lower levels of eotaxin, GM-CSF, GRO-α, IL-1β, IL-2, IL-5, IL-6, IL-12p70, IL-17A, IL-18, IP-10, MCP-1, MCP-3, MIP-1α, MIP-1β, MIP-2α, and TNF-α compared to unvaccinated controls." (PMID 41488663, 2025). "Pro-inflammatory cytokines (IL-1β, IL-6, TNF) surge while IL-10 drops in obesity." (PMID 41562075, 2025). "Obesity has been related to the chronic activation of proinflammatory signaling pathways, in which the NFκB is a critical component that controls the transcription and release of downstream pro‐inflammatory cytokines, such as IL‐6, TNF‐α, and IL‐1β." (PMID 39968210, 2025). "Additionally, obesity-induced inflammation activates the NLRP3 inflammasome, leading to increased secretion of IL-1β and IL-18, further promoting pro-inflammatory cytokine dysregulation and a tumorigenic microenvironment." (PMID 40722646, 2025). "Therefore, the intervention composition constitutes a promising safe and effective strategy for diminishing pro-inflammatory cytokines IL-1β and TNF-α in chronic inflammatory conditions, such as overweight/pre-obesity." (PMID 40430061, 2025). "Obesity fosters a state of chronic low-grade inflammation through adipose tissue dysfunction, characterized by the excessive secretion of pro-inflammatory cytokines such as IL-6, TNF-α, and IL-1β." (PMID 40004007, 2025). "However, obesity can contribute to IR over time, further increasing inflammatory markers such as TNF-α, IL-6, IL-1β, IL-18, and MCP-1." (PMID 40218960, 2025).
Obesity (continued). "An increase in pro-inflammatory cytokines (such as IL-1β), various glycation products (especially MGO and AGEs), oxidized LDL, and FFA contribute to glycemia, insulin resistance, dyslipidemia, and obesity through activation of the hepatic NF-kβ pathway and reduction in GLUT4 gene expression." (PMID 39877627, 2025). "Since LPS-mediated lncRNA29RIK could promote the production of IL-1β in the macrophages, we next employed HFD-mediated obesity model to detect the effects of lncRNA29RIK KO on the obesity." (PMID 40356927, 2025). "At the same time, adipocytes in the adipose tissue of patients with obesity can synthesize high levels of proinflammation cytokines, including TNF-α, LI-6, and IL-1β, which may induce systemic inflammation after entering the blood." (PMID 39722113, 2025). "Notably, IL-1β, IL-6, and TNF-α are major proinflammatory cytokines known to be involved in obesity-induced inflammation." (PMID 40118456, 2025). "Additionally, obesity promotes chronic inflammation, with adipose tissue acting as a source of pro-inflammatory cytokines such as TNF-α, IL-6, and IL-1β, which exacerbate lipid deposition in the liver." (PMID 40551780, 2025). "Notably, diabetes and obesity are always accompanied by chronic low‐grade inflammation, but JTTZF significantly reduced pro‐inflammatory cytokines (IL‐1β, TNF‐α and IL‐6) in diabetic mouse livers." (PMID 41250907, 2025). "Obesity induces a chronic low-grade systemic inflammatory state, wherein adipose tissue dysfunction leads to abnormal secretion of adipokines (e.g., leptin and adiponectin) and pro-inflammatory cytokines such as TNF-α, IL-6, and IL-1β." (PMID 41305576, 2025). "Overnutrition and obesity heighten systemic inflammation through adipokines and free fatty acids (FFAs), promoting macrophage infiltration and secretion of cytokines like TNF‐α and IL‐1β." (PMID 40673471, 2025). "Some studies suggest that a lower n-6:n-3 ratio may improve metabolic parameters in adolescents with obesity and fatty liver disease, enhance glucose and lipid metabolism in T2DM, and decrease serum levels of TNF-α, IL-1β, IL-6, and MCP-1." (PMID 40573106, 2025). "Whereas a reduction in both IL-1β and TNF-α was observed in the overweight/pre-obesity population in the intervention group, an increase in both cytokines was found in the overweight/pre-obesity population in the control group." (PMID 40430061, 2025). "In human studies, increased IL-1β expression in adipose tissue correlates with insulin resistance independent of obesity." (PMID 40943225, 2025). "In mice fed a HFHS diet that models obesity-driven MASLD, TFEB induction in KCs consistently led to a ~68% reduction in inflammatory MdM infiltration and decreased expression of inflammatory cytokine Il1b during early disease." (PMID 41665896, 2025). "Adipose tissue, especially in the context of obesity, acts as an immunologically active organ, releasing pro-inflammatory cytokines such as TNF-α, IL-6, and IL-1β, which impair insulin signaling, promote endothelial dysfunction, and contribute to vascular inflammation." (PMID 40870891, 2025). "In obesity, adipose tissue generates large amounts of pro‐inflammatory mediators, including leptin, resistin, retinol‐binding protein 4 (RBP4), lipocalin 2, and cytokines such as IL‐6, IL‐1β, and TNF‐α." (PMID 40673471, 2025). "In obesity, adipose tissue chronic inflammation promotes the secretion of proinflammatory cytokines, such as tumor necrosis factor alpha (TNF-α), interleukin (IL)-1β, IL-6, IL-17, and interferon (IFN)-γ, which prolong the extension of chronic inflammation in adipose tissues." (PMID 40863244, 2025). "Adipose tissue, particularly in the context of obesity, undergoes pathological expansion characterized by adipocyte hypertrophy, hypoxia, and stress responses that trigger the production of pro-inflammatory cytokines including TNF-α, IL-6, and IL-1β." (PMID 40551741, 2025).
Obesity (continued). "While PCOS increases IL-1β gene expression regardless of BMI, obesity intensifies the translation process, resulting in higher IL-1β protein levels in the serum of obese PCOS patients." (PMID 41411269, 2025). "Neither the pro-inflammatory factors TNF-α and IL-1β nor the secretome from patients with obesity (that is enriched in inflammatory mediators) exhibited an effect on the modulation of the NLRP6 inflammasome in the human enterocyte cell line CCL-241." (PMID 38315242, 2024). "In our study, IL-1β showed a weak and insignificant negative correlation with all indices representing indicators of obesity, except the WHR and VFL." (PMID 38257150, 2024). "Apart from demonstrating the capacity of IL-1β to predict hyperfiltration in patients with severe obesity, their study had another valuable result – patients in whom GFR did not normalize after MBS also showed failure to normalize circulating IL-1β/Caspase-1 levels." (PMID 39469576, 2024). "On the other hand, the mRNA levels of Il6 and Il1b did not elevate in the WAT of animals with obesity." (PMID 39004641, 2024). "As high fat and obesity potentially drive inflammation activation, so we detected the cytokine levels in HFD-fed mice’s hearts and found that IL-1β and IL-6 production was elevated in HFD-fed mice’s hearts, suggesting inflammation as a mediator in HFD-induced cardiac dysfunction." (PMID 39007149, 2024). "Obesity‐induced inflammation activates various signaling pathways, impairs insulin signaling, and promotes the release of proinflammatory mediators such as TNF‐α, IL‐1β, and IL‐6, all of which contribute to IR." (PMID 38812572, 2024). "Additionally, the systemic inflammatory markers, including levels of IL-1β, IL-1RA, IL-6, and TNF-α, were comparable between the overweight/obesity and healthy weight groups, suggesting similar inflammatory profiles regardless of weight status." (PMID 39201638, 2024). "To summarize, the activated inflammatory microenvironment, such as increased expression of IL‐1β and CXCL16, may promote obesity in LINK‐A overexpressing mice under HFD by affecting adipocyte thermogenesis." (PMID 38145352, 2024). "Obesity is a systemic chronic metabolic inflammation, with upregulation of inflammatory markers such as tumor necrosis factor (TNF-α), interleukins (IL)-6, IL-1β, and CCL2 in the adipose tissue of obese individuals." (PMID 39050542, 2024). "The obesity-related increase in VAT is characterized by the accumulation of macrophages, which are predominantly polarized M1 state and hence produce proinflammatory cytokines, including interleukin (IL)-1β, IL-6, and tumor necrosis factor-α (TNF-α)." (PMID 39201522, 2024). "In addition, obesity promotes the transition of macrophages to the M1 phenotype, which secretes more pro-inflammatory cytokines (e.g., TNF-α, IL-6, and IL-1β)." (PMID 39831058, 2024). "Adipocytes contribute to the secretion of proinflammatory cytokines such as TNF-α, IL-1β, MMP-2, MMP-9, IL-6, and MCP-1, as well as adipokines like adiponectin, which further contribute to chronic inflammation in adipose tissue of individuals with obesity." (PMID 38495901, 2024). "Adipose tissue in obesity secrets proinflammatory mediators such as TNF-α, IL-1β, and IL-6." (PMID 38317220, 2024). "Examination of the fibroinflammatory effects of obesity in MMP14LKO mice revealed that both WD and HFFC feeding in mice increased hepatic inflammatory marker gene expression—TNFα, CXCL2, CXCL9, TGFβ, and IL-1β—in WT mice, and this was attenuated in WD-fed MMP14LKO mice." (PMID 39282008, 2024). "We found that leukocyte and neutrophil counts were slightly higher in children with obesity but levels of IL‐1β and TNF‐α were not statistically significant." (PMID 40626250, 2024). "Thus, we propose that transient postprandial IL-1β surges regulate WAT remodeling by promoting adipogenesis, whereas chronically elevated IL-1β levels in obesity blunts this physiological function." (PMID 39261467, 2024).
Obesity (continued). "Together these findings indicate that MCC950 potently suppresses NP3 inflammasome-mediated IL-1β responses in systemic immune cells from all patients with asthma irrespective of disease severity and sex or obesity status." (PMID 38044426, 2023). "Therefore, in subsequent experiments, we used IL-1β as a marker to evaluate the effects of biogenic amines and hepatic damage in HFD-induced obesity." (PMID 36899958, 2023). "An increase in IL-1β, IL-18, TNF-α, inflammasome NLRP3 activation, astrogliosis, and BBB permeability in the brain areas involved in the control of the intake of food such as the LH and hippocampus are the hallmarks of obesity-induced neuroinflammation." (PMID 36674982, 2023). "We identified an increased risk of hepatic dysfunction by biogenic amine ingestion in obesity and confirmed that both blood and liver biomarkers, including CRP, MAO, IL-1β, and PARP-1, are helpful markers for evaluating hepatic function in biogenic amine-induced liver damage in obesity." (PMID 36899958, 2023). "Specifically, Vandanmagsar and collaborators described increased mRNA expression of NLRP3 and IL-1β (but not ASC) in AT from patients with obesity and T2D, and these levels correlated with glycemic state." (PMID 37819510, 2023). "Obesity induces a chronic low-grade inflammatory state, as does inflammaging, defined as age-related increases in pro-inflammatory cytokines, including TNF-α, IL-1β, and IL-6." (PMID 37681878, 2023). "A possible explanation for the effects on the Sertoli cell and sperm parameters is that severe obesity may trigger the activation of the NLRP3 inflammasome complex, leading to the production of the proinflammatory cytokines, IL-1β and IL-18." (PMID 36675601, 2023). "In the HFD-induced obesity model, aerobic exercise effectively suppressed the activation of the NLRP3 inflammasome in the left ventricles, consequently reducing expressions of NLRP3, ASC, pro-caspase-1, and IL-1β in the myocardium." (PMID 37859981, 2023). "Studies suggested that diet can affect inflammation and may produce clinically relevant endpoints in the form of increasing AHR, blocking IL-1β signaling with the IL-1 receptor antagonist anakinra, and reducing ILC3 and AHR in a mouse model of obesity." (PMID 38292857, 2023). "Different brain regions are affected by HFD; for example, in the hypothalamus, where the earliest activation occurs due to obesity (from day 1), the microglia lose their phagocytic capacity, while in the hippocampus, the expression of IBA1, CD45, CD68, MHC-II, and IL-1β increases." (PMID 36935429, 2023). "In any case, the NLRP3 inflammasome represents an interesting starting point for the therapy of low-grade inflammation in obesity and the availability of clinical antagonists of IL-1β opens new possibilities for the therapy of T2DM and cardiovascular diseases in the context of obesity." (PMID 37239938, 2023). "However, in the presence of high SFA levels, like they are present in obesity, S100A9 induces an inflammasome-dependent secretion of IL-1β by monocytes and macrophages as shown here for both mouse peritoneal macrophages and human monocytes." (PMID 35198063, 2022). "In OA combined with obesity, the subpatellar fat pad releases TNF-α, IL-6, IL-1, and IL-1β." (PMID 36439850, 2022). "Also obesity is recognized as a state of chronic inflammation with increased circulating pro-inflammatory cytokines tumour necrosis factor (TNF)-α, interleukin (IL)-1β and IL-6." (PMID 36614882, 2022). "Furthermore, kinase-inactive IRAKM reduced IL-1β-induced de novo fatty acid synthesis in adipocytes, and lipid accumulation in both WAT and BAT from HFD-fed mice to improve obesity-related pathophysiology." (PMID 35585086, 2022). "We show that SFA, which are increased in obesity, together with S100A9, an early danger molecule, induce IL-1β release in macrophages which in turn amplifies S100A9 expression initiating a vicious cycle of sustained S100A9 overexpression in skin inflammation in obesity." (PMID 35198063, 2022).